CDK4 (cyclin dependent kinase 4)
Diseases named in the same sentence as CDK4 in open-access papers (continued):
Sharing a sentence is not in itself a finding about the gene and the disease.
hepatocellular carcinoma (continued). "The protein levels of cyclin E, cyclin D, CDK2, and CDK4 were dramatically induced upon knockdown of LINC01488 in hepatoma cells." (PMID 32575745, 2020). "Whereas, it has been reported that Numb promotes cell proliferation and cell cycle of hepatocellular carcinoma, inhibiting p21 and modulating CDK4 and SKP2." (PMID 30034624, 2018). "It reported that has-miR-195-497 cluster was intracellular antagonists of BMP signaling pathway in bone cells in and targeting cell cycle proteins CDK6, CCNE1, CDC25A and CDK4 to regulated cell proliferation in human hepatocellular carcinoma cells." (PMID 27384321, 2016). "The suppression of ARID2 expression in hepatoma cells facilitated G1/S transition associated with transcriptional upregulation of E2F1, cyclin D1, and cyclin E1, induction of CDK4, and phosphorylation of Rb." (PMID 27351279, 2016). "Here, we report that upon glucose induction, protein arginine methyltransferase 5 (PRMT5) exerts a profound effect on the G1-S cell cycle progression via directly interacting with cyclin dependent kinase 4 (CDK4) in hepatocellular carcinoma (HCC)." (PMID 27708221, 2016). "Various studies showed that WIN55212-2 has pro-apoptotic effects and results in growth arrest and downregulation of cell cycle dependent kinases like cdk2, cdk4 and cdk6 in different tumor cell lines such as HepG2 hepatoma cells." (PMID 22204398, 2011). "Canagliflozin-treated HepG2 cells demonstrated increased expression of the cell growth regulator hepatocyte nuclear factor 4 (HNF4), with a reduced expression of cyclin D1, cyclin D2, and cdk4, resulting in cell cycle arrest in a hepatocellular carcinoma (HCC) cell line." (PMID 40869400, 2025). "In addition, CDK4 expression correlated with expression of the inhibitory receptor of phagocytosis CD47 in immunohistochemistry sections from hepatocellular carcinomas." (PMID 40699853, 2025). "CDK2 and CDK4 are involved in the toxic action of paclitaxel on human hepatoma cells." (PMID 41002596, 2025). "Additionally, CDK4 inhibitors can significantly reduce the tumor size and weight of transplanted hepatocellular carcinoma in nude mice." (PMID 38231074, 2025). "It has also been shown that CDK4 can bind to survivin to form a complex, releasing substances that bind to caspase-3 and inhibit the activity, which has the effect of preventing apoptosis in hepatocellular carcinoma cells." (PMID 37108294, 2023). "Furthermore, reduced expression of cyclin D1, cyclin D2 and cdk4 leading to cell cycle arrest in a hepatocellular carcinoma (HCC) cell line have been reported after treatment with canagliflozin." (PMID 35328527, 2022). "For example, the circ_0016788/miR-486/CDK4 axis regulates hepatocellular carcinoma tumorigenesis." (PMID 33504681, 2021). "In regard to the Rb-independent effects, has been also reported that the CDK4/6 inhibitor Palbociclib induces a significant cell cycle arrest in Rb-silenced HepG2 and Hu7 hepatocellular carcinoma cell lines, as well as induces apoptosis of T-acute lymphoblastic leukaemia and bladder cancer cells." (PMID 33213401, 2020). "A previous study of hepatocellular carcinoma cells demonstrated that palbociclib induced autophagy in a CDK4/6-independent manner; in those cells, autophagy was induced via a mechanism involving 5′ AMP-activated protein kinase (AMPK) activation and protein phosphatase 5 (PP5) inhibition." (PMID 33243298, 2020).
hepatocellular carcinoma (continued). "Furthermore, it was discovered that the CDK4 inhibitor may effectively decrease the expression of CDK4 in hepatoma cell lines and display greater tumor cytotoxicity and a lower IC50 value than sorafenib." (PMID 38231074, 2025). "Similar pathway aberrations are frequently observed in hepatocellular carcinoma (HCC), suggesting potential therapeutic applications for CDK4/6 inhibitors in this context as well." (PMID 40456804, 2025). "In hepatocellular carcinoma HepG2 cells, it enhances the expression of miR-497-5p, which can target the 3′-UTR of the cyclin-dependent kinase 4 (CDK4) mRNA, leading to decreased levels of this kinase and increased cell proliferation." (PMID 41226811, 2025). "CHEK1, CDC25A, and CCNE1, together with CCND1, CCND3, CDK4, CDK6, BTRC, E2F3, and FOXK1, were previously identified as the targets of miR‐497∼195 cluster in hepatocellular carcinoma." (PMID 40548926, 2025). "Forced expression of miR-198 in hepatoma cells inhibits the expression of the signal transducer genes c-MET and CDK4, which promote proliferative pathways, and increases the expression of E-cadherin and claudin-1, which maintain cellular adhesion." (PMID 41465470, 2025). "Phosphorylation of the newly substituted serine at this position by CDK4/6 creates a binding site for MYC and increases ribosomal biogenesis in hepatocellular carcinoma cells." (PMID 40699853, 2025). "Additionally, a CDK4 inhibitor may have anti-tumor properties against hepatocellular cancer." (PMID 38231074, 2025). "Huang’s group showed that competitive inhibition of the interaction between CDK4 and CDKN2A by PRMT5 is essential for glucose-induced hepatocellular carcinoma cell proliferation." (PMID 39255317, 2024). "Intriguingly, a positive correlation between cell cycle regulatory protein CDK4 and JMJD6 expression was identified, and mechanistic analysis indicated JMJD6 enhanced CDK4 expression in hepatocellular carcinoma by directly binding to its promoter." (PMID 38166895, 2024). "Other studies have revealed that miR-122 is a tumor suppressor through modulating oncogenes including CDK4, cyclin G1, and AKT3 in hepatocellular carcinoma (HCC)." (PMID 35651814, 2022). "For example, miR-124-3p reduced the progress of hepatocellular carcinoma by inhibiting the expression of target genes, such as CDK2 and CDK4." (PMID 34582363, 2021). "As a natural antisense transcript of cyclin-dependent kinase 4 (CDK4), TSPAN31 regulates the expression of CDK4 mRNA and protein in hepatocellular carcinoma cells (HCC)." (PMID 32507938, 2020). "In summary, the present work show that daphnegiravone D markedly suppress the proliferation and survival of hepatoma cells, and induce G0/G1 arrest by reducing the expression of cyclin E1, CDK2 and CDK4 in a p38-dependent manner." (PMID 28720813, 2017). "Overall, the CDK4 and CDKN2A (p16INK4a as the major isoform) complex is more critical for growth suppression in hepatoma cells or other types of tumor cells." (PMID 27708221, 2016). "Furthermore, MAPK1, E2F2, CDK4, CDKN1A, CCND1 were found key target genes of hepatocellular carcinoma pathway." (PMID 33959508, 2021). "CDK2, CDK4, CCNB1 and CCND1 can accelerate the cell cycle moving from G1 to S phase and then promote the proliferation of various cell types including mouse embryonic fibroblasts, mouse neural progenitor cells and human hepatocellular carcinoma." (PMID 34438874, 2021). "An oleanane-type saponin oleiferasaponin C6 from Camellia oleifera seeds was found to induce cell cycle arrest at the G0/G1 phases through regulating p21, cyclin-dependent kinase 4 (CDK4) and cyclin D1 in human promyelocytic leukemia HL-60 cells and hepatocellular carcinoma BEL-7402 cells." (PMID 33802884, 2021).
metastatic disease (80 papers, 2015 to 2026). "The cyclin dependent kinase, CDK4, was also found to be associated with metastatic disease recurrence in our patient population." (PMID 36464833, 2023). "Single-cell RNA sequencing analyzed metastatic tumors from HR+/HER2- mBC patients pre-CDK4/6i treatment at baseline (BL) and/or at disease progression." (PMID 39955556, 2025). "Although these patients typically receive standard hormone therapy, CDK4/6is are also commonly used in cases of more advanced or metastatic tumors." (PMID 41161384, 2025). "Our cohort included both patients who initiated CDK4/6 inhibitors as first-line therapy for de novo metastatic disease and those who experienced recurrence after prior adjuvant endocrine therapy." (PMID 40907238, 2025). "Organized screening has further improved outcomes by promoting earlier detection, while targeted treatments—including anti-HER2 agents, CDK4/6 inhibitors, and novel endocrine or immune therapies—have extended survival even in metastatic disease." (PMID 41514620, 2025). "Younger patients, biopsies of metastatic disease and with multiple metastatic sites were more frequently treated with CDK4/6i in our daily clinical practice." (PMID 38831191, 2024). "Initiation of chemotherapy (capecitabine or IV chemotherapy) for treatment of metastatic disease was significantly different in patients who received 1st-line CDK4/6i versus those who received 2nd-line CDK4/6i (p-value < 0.001)." (PMID 38922546, 2024). "In HR+/HER2− metastatic tumors, the PI3KCA mutations are present in around 40% of cases, and endocrine therapy and cyclin-dependent kinase 4 and 6 (CDK4/6) inhibitors are the standards of care to treat these tumors." (PMID 38337803, 2024). "Our nonchemotherapy group was very small and had very poor outcomes; however, the duration from the diagnosis of metastatic disease to the completion of CDK4/6i therapy correlated with the later initiation of chemotherapy." (PMID 39199665, 2024). "Median OS since the diagnosis of metastatic disease was 4.5 years (95% CI 3.9–6.3), median OS since the start of CDK4/6 treatment was 3.7 years (95% CI 3.4–4.4), while median OS from initial cancer diagnosis was 15.8 years (95% CI 13.8–18.3)." (PMID 39338149, 2024). "OS in our study since the diagnosis of metastatic disease was 4.5 years (95% CI 3.9–6.3), median OS since the start of CDK4/6 treatment was 3.7 years (95% CI 3.4–4.4), while median OS from initial cancer diagnosis was 15.8 years (95% CI 13.8–18.3)." (PMID 39338149, 2024). "The amplification of CDK4 (p = 0.090) and MDM2 (p = 0.067) was found to be associated with an increased risk of metastatic disease." (PMID 36464833, 2023). "It should be noted that the patient population treated in this study were naive to CDK4/6 inhibitors which are now used routinely in the first-line treatment of metastatic disease alongside aromatase inhibitors." (PMID 39516358, 2023). "Camizestrant 10 mg/kg daily was profiled in 28 PDX models, and head-to-head with fulvestrant at 5 mg/weekly in 25 ER+ PDX models derived from primary or metastatic tumors, naïve or exposed to ET and/or CDK4/6i, and with various ESR1m status." (PMID 37725704, 2023). "The combination of the aromatase inhibitor with a CDK4/6 inhibitor was used for one patient who had metastatic disease with the addition of bisphosphonate for bone metastasis." (PMID 38146568, 2023). "The majority had claims records of metastatic disease and received ET prior to their first use of a CDK4 and 6 inhibitor." (PMID 36414795, 2023). "Nonetheless, a significant challenge that limits the efficacy of CDK4/6i treatment is the occurrence of acquired resistance that leads to the progression of metastatic disease." (PMID 36765648, 2023). "We observed that patients with secondary metastatic disease displayed a shortened PFS following CDK4/6i therapy than those who had de novo metastatic disease." (PMID 36876172, 2023).
metastatic disease (continued). "Statement 5 (In case of visceral crisis and ab initio metastatic disease with high hormonal receptor expression, can an ET + CDK4/6i be proposed over a “rescue” chemotherapy)?" (PMID 36158652, 2022). "Of the 144 patients, 80 (56%) patients had received no prior line, 29 (20%) patients had received 1 prior line, and 35 (24%) patients had received 2+ lines of treatment for metastatic disease prior to starting CDK4/6i." (PMID 35804935, 2022). "Only 4 (11.1%) patients received CDK4/6 inhibitor-based therapy as first-line treatment for their metastatic disease." (PMID 36042494, 2022). "We aim to clarify the incidence of AIMSS in AI monotherapy treatment in postmenopausal women with metastatic disease and the impact of the recent addition of CDK4/6 inhibitors on this common adverse event." (PMID 33530456, 2021). "Of note, most of the organoids derived from metastatic tumors show resistance to palbociclib (CDK4/6 inhibitor) and cepharanthine (inhibiting TNF‐α‐mediated NFκB stimulation)." (PMID 34605222, 2021). "Overall, median PFS was 12.6 months (95% CI; 1.34–23.85) for patients treated with CDK4/6 inhibitors for metastatic disease." (PMID 34198899, 2021). "The proportion of elderly patients presenting with de novo metastatic disease in this study is comparable to that seen in other studies of CDK4/6 inhibitors [6,8,]." (PMID 34736090, 2021). "And so, considering the option of postponing a line of CDK4/6 inhibitors, for bone only, low burden, de novo metastatic disease, particularly in the elderly." (PMID 33608590, 2021). "Bone pain reported in patients receiving CDK4/6 inhibitors is decreased compared with patients treated with AIs for metastatic disease." (PMID 33530456, 2021). "The incidence of back pain was 7–32.9% vs. 2.9–8.5% in postmenopausal women with metastatic disease treated with AIs and CDK4/6 inhibitors, respectively." (PMID 33530456, 2021). "However, gene analysis showed that only 6% of ER+/HER2− ABC harbored FAT1 loss-of-function mutations in their metastatic tumors after treatment with CDK4/6i, likely representing a small population of patients with resistance to CDK4/6i, and the predictive value FAT1 mutations remain unclear." (PMID 34771560, 2021). "Based on the changes in the expression of HIF-1α, CDK4, and C-Myc in metastatic tumors, we assumed that this regulation is related to ubiquitination degradation." (PMID 32796813, 2020). "The majority of participants received CDK4/6i for advanced or metastatic disease (54/76, 71%)." (PMID 40315425, 2025). "At the start of CDK4/6 inhibitor therapy, all patients presented with metastatic disease." (PMID 39456537, 2024). "In addition, in metastatic disease, 80 patients received treatment with CDK4/6 inhibitors + endocrine therapy: 61 in the first line and 19 in the second line." (PMID 39235099, 2024). "In addition, next-generation SERMs (e.g., lasofoxifene, bazedoxifene) are being developed as monotherapies and combined with CDK4/6i for advanced metastatic disease." (PMID 37725704, 2023). "A total of 80% of the patients received CDK4/6 as their initial therapy for metastatic disease." (PMID 36405937, 2022). "As CDK4/6 inhibitors represent standard-of-care therapeutics for patients with ERα-positive metastatic disease who relapsed after prior endocrine therapeutics, the phase of the disease in which ERα mutations are most apparent, we focused on ribociclib for downstream analyses on ERα-WT and ERα-MutA." (PMID 34944934, 2021). "One possible interpretation of our data is that CDKN1B amplification in primary tumors acts to slow the rate of tumor proliferation and metastasis, which would point toward the possible utility of CDK4/6 inhibitors as a means of delaying progression to metastatic disease." (PMID 32374727, 2020).
metastatic disease (continued). "A median PFS of 7.4 months was observed despite the fact that more than half of the patients had had prior hormonal treatment, almost 20% of patients had had prior chemotherapy, and 30% of patients had previously received a CDK4/6 inhibitor for metastatic disease." (PMID 31849202, 2020). "In addition, because combined therapy with CDK4/6 inhibitors and endocrine therapy are now frequently used as first-line treatment of patients with metastatic disease, an important area for therapeutic intervention is in patients who have become resistant to these treatments." (PMID 35688802, 2022). "Noteworthily, ESMO recommendations reported that postponing the incorporation of a CDK4/6 inhibitor in the first line for patients presenting with special patterns of disease (eg, bone only, low burden, de novo metastatic disease) could be an option, especially in the older population." (PMID 34726611, 2021). "Indeed with the development of spliceosome inhibitors themselves, and exciting preclinical data in other tumour types highlight a potential novel treatment strategy in combination with endocrine therapy and CDK4/6 inhibitors for patients with metastatic disease with spliceosomal gene alterations." (PMID 29848666, 2018). "Patients with HR + metastatic disease had a median of 1 prior line of endocrine therapy (ET) for metastatic disease (IQR 0 − 2), with cyclin-dependent kinase 4/6 (CDK4/6) inhibitors in combination with ET (44.6%) being the most common therapy." (PMID 40931303, 2025). "Here, we report the successful treatment of HR-negative/HER2-positive primary tissue and HR-positive/HER2-negative metastatic disease after T-DM1 and T-Dxd treatment using a CDK4/6 inhibitor." (PMID 39429386, 2024). "Palbociclib is a selective CDK4/6 inhibitor used to treat patients with ER-positive, HER2-negative metastatic disease but has also been studied as adjuvant therapy in several clinical trials." (PMID 36574653, 2023). "In patients with metastatic diseases, germline BRCA1/2 genotyping should probably be initiated early when the endocrine therapy combined with CDK4/6 inhibitor is started." (PMID 35158866, 2022). "The majority of approvals were in metastatic disease (76%); in this setting, more than 60% were issued in hormone receptor-positive/HER2-negative patients and of them, 80% concerned a CDK4/6 inhibitor." (PMID 34680350, 2021). "Two patients who had been diagnosed with metastatic disease prior to the accrual period had received multiple lines of therapy for metastatic disease, but none of these treatments included CDK4/6i." (PMID 39865083, 2025). "Characterizing metastatic tumors solely based on ER positivity or ESR1 status is insufficient, and there is a need for improved methodologies to select patients who remain endocrine sensitive after CDK4/6i treatment." (PMID 38800404, 2024). "The nivolumab cohort for patients with microsatellite instable metastatic tumors proved highly successful with a CBR of 63%, while palbociclib or ribociclib in patients with tumors harboring CDK4/6 pathway alterations showed limited efficacy, with a CBR of 15%." (PMID 38779868, 2024). "Furthermore, among ER-positive patients treated with CDK4/6 inhibitors, superior PFS and OS outcomes are observed in patients with de novo metastatic disease." (PMID 38912829, 2024). "Based on our multi-OMICS pipeline, CDK4/6 hyperactivation and BETs were prioritized as targets of interest for in vivo screening since both signatures are present in OS PDX derived from patients with aggressive and metastatic disease." (PMID 36612255, 2022). "Further, to identify the role of the factors in motifs with good predictive power (CDK4/SNHG5/hsa-let-7a-3p and UCA1/AKT1/hsa-miR-125b-1) in the regulation of various metastatic tumors, we used Target Mine web server and selected BH method (Benjamini-Hochberg) for P-value adjustment." (PMID 32703153, 2020).